PSAT1 (phosphoserine aminotransferase 1)
Diseases named in the same sentence as PSAT1 in open-access papers (continued):
Sharing a sentence is not in itself a finding about the gene and the disease.
colon carcinoma (19 papers, 2008 to 2024). "For example, in colon cancer cell lines, miRNA-145-5p can regulate the expression of phosphoserine aminotransferase 1 (PSAT1) and inhibit the proliferation of colon cancer cells." (PMID 38892156, 2024). "Nadia reported that the overexpression of PSAT1 significantly stimulated the cell growth of colon cancer cells." (PMID 36732787, 2023). "PSAT1 expression is elevated in colon cancer and lung adenocarcinoma, and has been shown to enhance cell proliferation, metastasis, and chemoresistance." (PMID 36793607, 2023). "MicroRNA-145-5p and phosphoserine aminotransferase 1 (PSAT1) levels in colon cancer cells were assayed via quantitative reverse transcription polymerase chain reaction (qRT-PCR)." (PMID 35615948, 2022). "This study attempted to investigate the effect of microRNA-145-5p/PSAT1 on colon cancer proliferation and cycle." (PMID 35615948, 2022). "Overall, this study highlighted that microRNA-145-5p inhibited PSAT1 level and cell proliferation in colon cancer." (PMID 35615948, 2022). "Next, the relationship between PSAT1 and the cell cycle of colon cancer cells was analyzed by flow cytometry." (PMID 35615948, 2022). "The result of qRT-PCR disclosed that microRNA-145-5p was markedly down-regulated and PSAT1 level was up-regulated in colon cancer cell lines." (PMID 35615948, 2022). "Endogenous silencing of PSAT1 blocked colon cancer cells from entering S phase, thereby inhibiting cell proliferation in vitro." (PMID 35615948, 2022). "Concludingly, the findings indicated that overexpressed PSAT1 shortened the G1 phase of the cell cycle and advanced cells into S phase, thereby enhancing the proliferation of colon cancer cells." (PMID 35615948, 2022). "Taken together, microRNA-145-5p regulated cell cycle through PSAT1 to inhibit colon cancer cell proliferation." (PMID 35615948, 2022). "The effects of microRNA-145-5p and PSAT1 on colon cancer cell cycle and proliferation were detected by CCK-8, colony formation, and flow cytometry." (PMID 35615948, 2022). "Consistent with previous studies, PSAT1 here was remarkably upregulated in colon cancer cells, and in vitro cell experiments indicated that overexpressed PSAT1 fostered colon cancer cell proliferation." (PMID 35615948, 2022). "The results manifested that microRNA-145-5p restrained colon cancer cell cycle progression and proliferation, and PSAT1 fostered colon cancer cell cycle progression and cell proliferation." (PMID 35615948, 2022). "The results indicated that there were specific binding sites for microRNA-145-5p on the 3’-UTR of PSAT1, suggesting that PSAT1 was the target gene of microRNA-145-5p in colon cancer." (PMID 35615948, 2022). "It was previously verified that PSAT1 was upregulated in colon cancer cells and inversely modulated by microRNA-145-5p." (PMID 35615948, 2022). "Taken together, our findings demonstrated that microRNA-145-5p repressed colon cancer cell cycle progression and cell proliferation via targeting PSAT1." (PMID 35615948, 2022). "Taken together, our findings demonstrated that microRNA-145-5p restrained colon cancer cell cycle progression and cell proliferation via targeting PSAT1." (PMID 35615948, 2022). "Firstly, mimic NC+oe-NC, microRNA-145-5p mimic+oe-NC, and microRNA-145-5p mimic+oe-PSAT1 were transfected into colon cancer cell line HT29, respectively." (PMID 35615948, 2022). "This study aimed to investigate the effect of the microRNA-145-5p/PSAT1 axis on the proliferation and cycle of colon cancer cells." (PMID 35615948, 2022). "Previous studies have shown that PSAT1 plays a vital role in cell proliferation as it acts as an oncogene in colon cancer and NSCLC." (PMID 29216929, 2017). "PSAT1 was found to be up-regulated in colon cancer, esophageal squamous cell carcinoma (ESCC) and non-small cell lung cancer (NSCLC), and has been shown to enhance cell proliferation, metastasis and chemoresistance, which all contribute to a poor prognosis." (PMID 29216929, 2017).
colon carcinoma (continued). "PSAT1 is overexpressed in colon cancers where it contributes to cell proliferation and chemoresistance, which result in a poor prognosis." (PMID 29216929, 2017). "Up-regulation of PSAT1 stimulates cell growth and increases chemoresistance of colon cancer cells to L-OHP." (PMID 26515599, 2015). "In experiments using human cell lines, we showed that ectopic PSAT1 overexpression in colon carcinoma SW480 cell line resulted in an increase in its growth rate and survival." (PMID 18221502, 2008). "In this study, we observed that the phosphoserine aminotransferase PSAT1 is overexpressed in colon carcinoma compared with normal mucosa." (PMID 18221502, 2008). "Two studies reported that PSAT1 mRNA is overexpressed in colon adenocarcinoma and increases with tumor stage in colon cancer." (PMID 18221502, 2008). "But, the correlation between PSAT1 and microRNA-145-5p in colon cancer is warranted." (PMID 35615948, 2022). "Notably, our study revealed for the first time that microRNA-145-5p modulated colon cancer malignant progression in vitro via targeting PSAT1." (PMID 35615948, 2022). "Thus, low expression of microRNA-145-5p in colon cancer was assayed by qRT-PCR, and PSAT1 level was up-regulated." (PMID 35615948, 2022). "Therefore, based on bioinformatics analysis and a series of biological experiments, we found that microRNA-145-5p was underexpressed in colon cancer, and the expression of PSAT1, which is a downstream target of microRNA-145-5p, was up-regulated." (PMID 35615948, 2022). "Other studies found that PSAT1 mRNA is upregulated with colon cancer progression." (PMID 35615948, 2022). "This newly discovered microRNA-145-5p/PSAT1 regulatory axis may offer new strategies for colon cancer management." (PMID 35615948, 2022). "It was also noted that PSAT1 was conspicuously overexpressed in colon cancer tissue." (PMID 35615948, 2022). "MicroRNA-145-5p targeted PSAT1 to hinder cycle progression in colon cancer." (PMID 35615948, 2022). "We focused on regulatory relationship between microRNA-145-5p and PSAT1, which may furnish a novel regimen for colon cancer management." (PMID 35615948, 2022). "Overexpression of PSAT1 enhances chemoresistance and promotes cell growth of colon cancer." (PMID 33526036, 2021). "PSAT1 is over-expressed in colon tumors, but its role in PCP cannot be speculated due to limited information on its function." (PMID 20377877, 2010). "Recently, it has been shown that PSAT1 overexpression stimutated cell growth of colon cancer cells." (PMID 19671193, 2009). "We then investigate the PSAT1 expression level in colon cancer cell lines." (PMID 18221502, 2008). "PSAT1 also is involved in the process by which colon cancer cells acquire chemotherapy resistance." (PMID 18783612, 2008). "We first observed that PSAT1 is overexpressed in colon tumors." (PMID 18221502, 2008). "PSAT1 was over-expressed in colon tumors, and may be a new target for CRC therapy." (PMID 24516561, 2014). "In addition, PSAT1 was reported to be overexpressed in some types of tumours and could affect the proliferation or invasion of cancer cells, including esophageal squamous cell carcinoma, colon cancer, and non-small cell lung cancer cells." (PMID 36732787, 2023). "Little is known about EBV-miRNAs in colon cancer, however, miR-BART19-3p is shown to target WIF1, a gene important in colon cancer, and miR-BART1 is shown to target PSAT1, a gene shown to promote proliferation of tumor cells." (PMID 30786859, 2019). "This phenomenon contrasts with that seen in the upstream metabolic enzyme PSAT1, in which overexpression of the protein stimulates cell growth, increases tumorigenicity and promotes chemo-resistance in SW480 colon carcinoma cells." (PMID 27391339, 2016). "The SW480-PSAT1 tumor grew much faster than the SW480-FlpIn tumor, indicating that colon cancer cells overexpressing PSAT1 proliferated faster in vivo, as was also the case in vitro." (PMID 18221502, 2008).
colon carcinoma (continued). "Furthermore, five of the seven glycolytic and PPP enzymes identified in our interactome analysis (GOT2, GPI, PGD, PSAT1, and TKT) were found to map to the “Metabolic reprogramming in colon cancer” pathway." (PMID 30108113, 2018). "PSAT1 was expressed in all the colon cancer cells tested, with the lowest expression level found in normal colon." (PMID 18221502, 2008).
non-small cell lung carcinoma (18 papers, 2017 to 2025). A group of at least three distinct histological types of lung cancer, including non-small cell squamous cell carcinoma, adenocarcinoma, and large cell carcinoma. "Furthermore, studies have shown that the up-regulation of PSAT1 promotes cell proliferation and is associated with a poor outcome in patients with non-small cell lung cancer." (PMID 38614981, 2024). "PSAT1 overexpression is documented across multiple malignancies — including non-small cell lung cancer (NSCLC), breast cancer, gastric cancer, colon cancer, and ovarian cancer — where it drives tumorigenesis and malignant progression." (PMID 40265021, 2025). "The expression of PSAT1 is inhibited by miR-15a-5p and miR-15b-5p in non-small cell lung cancer (NSCLC)." (PMID 37127605, 2023). "Yang proved that PSAT1 strongly promoted the cell cycle progression and cell proliferation of non-small cell lung cancer cells." (PMID 36732787, 2023). "PHGDH and PSAT1 are activated in non-small cell lung cancer, leading to changes in the metabolic pathways of serine." (PMID 36464703, 2022). "Moreover, an in vitro study on human cell lines showed that silencing the PSAT1 gene resulted in the inhibition of tumor proliferation and growth in non-small cell lung cancer." (PMID 38203636, 2023). "ATF4 transcriptionally activates serine biosynthetic genes in response to serine starvation in non-small cell lung cancer, and additionally, it has been shown to play a crucial role in the regulation of PSAT1 after OSN (Oct4, Sox2, and Nanog) was expressed in mouse embryonic stem cells." (PMID 29216929, 2017). "Human non-small cell lung cancer with high NRF2 protein expression displayed significantly higher expression of ATF4, PHGDH, PSAT1, and SHMT2, which was significantly related to poorer prognosis and higher tumor grade." (PMID 32226297, 2020). "Furthermore, PHGDH, PSAT1, PSPH, and SHMT have been shown to be direct transcriptional targets of ATF4 which was transcriptionally activated by NRF2 in a non-small-cell lung cancer model." (PMID 31615983, 2019). "Interestingly, a potential link between PSAT1 and PSRC1 has been found in previous studies of non-small cell lung cancer, in which increased PSAT1 expression inhibits the degradation of the cell cycle protein d1, while elevated PSRC1 expression promotes the production of this protein." (PMID 39872525, 2024).
colorectal cancer (17 papers, 2008 to 2025). A primary or metastatic malignant neoplasm that affects the colon or rectum. "In colorectal cancer, phosphoserine aminotransferase 1 (PSAT1) levels have been implicated in poor prognosis." (PMID 31980738, 2020). "However, co-culturing CD8+ T cells with Psat1- or Shmt2-deficient colorectal cancer cells showed enhanced cytotoxic activity, as indicated by increased Granzyme B levels detected via flow cytometry." (PMID 40475762, 2025). "It is interesting to note that among all amino acids, serine, as the primary precursor of glutathione, plays a vital function in colorectal cancer progression and chemoresistance, and that an increase in PSAT1 enzyme expression after chemotherapy is associated with tumor progression in CRC patients." (PMID 41234632, 2025). "Upregulation of PSAT1 in cervical, ovarian, and colorectal cancers activates the PI3K/AKT signaling pathway, thereby improving cellular redox balance and enhancing the repair of cisplatin-induced DNA damage." (PMID 41469472, 2025). "Small interfering RNAs (siRNAs) were used to individually knock down Psat1 and Shmt2 in two murine colorectal cancer cell lines (CT26 and MC38), with knockdown efficiency confirmed by RT-qPCR and Western blot." (PMID 40475762, 2025). "This intricate interplay ultimately influences the progression of colorectal cancer, highlighting the potential of PSAT1 as a promising therapeutic target for the treatment of CRC." (PMID 38706897, 2024). "These collective findings suggest that PSAT1 tends to exhibit a relatively low expression profile in the majority of colorectal cancer cell lines." (PMID 38706897, 2024). "In our current investigation, we have identified that PSAT1 exhibits low expression in colorectal cancer cells and CRC tumor samples." (PMID 38706897, 2024). "Further experimentation involving the knockdown of PSAT1 in colorectal cancer cells revealed a down-regulation of E-cadherin expression and an upregulation of α-SMA expression." (PMID 38706897, 2024). "The relationship between PSAT1 and EMT in colorectal cancer, as well as the underlying molecular mechanisms, remains enigmatic and warrants thorough exploration." (PMID 38706897, 2024). "It is worth noting that our analysis also revealed a positive association between PSAT1 expression and Recurrence-Free Survival (RFS) in colorectal cancer patients." (PMID 38706897, 2024). "In summary, our study has unveiled the substantial impact of PSAT1 on the invasion and migration of colorectal cancer cells, shedding light on its role in regulating the EMT process through its interaction with the PI3K/AKT signaling pathway." (PMID 38706897, 2024). "By employing this diverse array of investigative techniques, we were able to achieve a comprehensive comprehension of the multifaceted role that PSAT1 plays in the pathogenesis of colorectal cancer." (PMID 38706897, 2024). "In colorectal cancer cells, overexpression of PSAT1 induces enhanced tumorigenic properties compared to control cells in a xenograft mouse model and confers resistance to oxaliplatin treatment." (PMID 35011702, 2022). "In colorectal cancers, PSAT1 is considered the most upregulated gene and its overexpression is linked to advanced tumor stage, chemo-resistance and poor prognosis with endocrine therapy." (PMID 36105075, 2022). "In this work our aim was to study the role of the phosphoserine aminotransferase PSAT1 in colorectal cancer development." (PMID 18221502, 2008). "In summary, our results point to PSAT1 as a novel gene that stimulates colorectal cancer cells proliferation and modulates chemotherapy sensitivity, both in vitro and in vivo." (PMID 18221502, 2008). "To investigate the role of PSAT1 in colorectal cancer, we first analyzed the PSAT1 mRNA expression in tumors from 29 patients with advanced colorectal cancer." (PMID 18221502, 2008).
colorectal cancer (continued). "Additionally, through Kaplan-Meier analysis, we uncovered a distinct correlation between PSAT1 expression and the prognosis of colorectal cancer patients." (PMID 38706897, 2024). "Previous research reported that the dysregulation of PSAT1 activity may alter glucose and glutamine utilization in serine biosynthesis, promoting tumorigenesis and chemoresistance in colorectal cancers given that PSAT1 is a metabolism-related gene." (PMID 38614981, 2024). "Additionally, PSAT1 stimulates colorectal cancer cell proliferation and modulates chemotherapy sensitivity both in vitro and in vivo." (PMID 38475473, 2024). "Consequently, these compelling results provide strong evidence that the PI3K/AKT inhibitor LY294002 can effectively reverse the functional effects exerted by PSAT1 in colorectal cancer cells." (PMID 38706897, 2024). "Furthermore, we have established a positive correlation between the expression levels of PSAT1 and the overall survival rates among individuals afflicted by colorectal cancer." (PMID 38706897, 2024). "The results from Western blot analysis yielded noteworthy findings, indicating that the protein expression levels of PSAT1 were notably lower in various colorectal cancer cell lines (HCT8, HCT116, SW620, SW480, and HT29) when compared to human normal colonic epithelial cells (NCM460)." (PMID 38706897, 2024). "However, since the mechanism of action of PSAT1 in CRC is still unclear, it is important to study the development of PSAT1 in colorectal cancer cells." (PMID 38706897, 2024). "Similarly, both depletion of PSAT1 in colorectal cancer cells and removal of serine from mouse diet inhibit tumor growth and increase the antitumor efficacy of 5-FU in vivo." (PMID 35011702, 2022). "The expression of PSAT1 was significantly increased in colorectal cancer." (PMID 36105075, 2022). "G9A-mediated PSAT1 controlled supports cell proliferation of colorectal cancer." (PMID 33526036, 2021). "MiR-424 targets PSAT1 and possesses an inhibited function in colorectal cancer." (PMID 33526036, 2021). "The study reported herein suggest that PSAT1 may be a gene whose expression pattern before and after treatment is associated with poor response to FOLFIRI in colorectal cancer patients." (PMID 18221502, 2008). "For KIRC, the highest-scoring differentially co-expressed gene was PSAT1 (phosphoserine aminotransferase 1), a key enzyme in the serine biosynthesis pathway which has already been associated with breast and colorectal cancers before, but has not yet been associated with kidney cancer." (PMID 25961905, 2015). "Targeting PSAT1 to regulate the occurrence, proliferation, invasion, and EMT process of colorectal cancer represents a novel therapeutic approach." (PMID 38706897, 2024). "In light of these findings, the exploration of the relationship between PSAT1 and EMT holds significant promise and may offer novel insights for the clinical management of colorectal cancer." (PMID 38706897, 2024).
esophageal squamous cell carcinoma (12 papers, 2017 to 2024). Esophageal squamous cell carcinoma (ESCC) is a type of esophageal carcinoma (EC) that can affect any part of the esophagus, but is usually located in the upper or middle third. "Increased PSAT1 expression was significantly associated with stage of disease and metastasis in human esophageal squamous cell carcinoma (ESCC)." (PMID 33291071, 2020). "In an esophageal squamous cell carcinoma xenograft mouse model, phosphoserine aminotransferase (PSAT1) was identified as being directly regulated by miR-340." (PMID 36013278, 2022). "In esophageal squamous cell carcinoma, PSAT1 was identified as an potential anticancer therapeutic target." (PMID 29297280, 2017). "Notably, ectopic expression of MEG3 has demonstrated the ability to significantly inhibit the proliferation, migration, invasion, and EMT of esophageal squamous cell carcinoma (ESCC) cells by down-regulating PSAT1 expression." (PMID 38706897, 2024). "Interestingly, lncRNA MEG3 exerts tumor-suppressive effects and inhibits Epithelial-mesenchymal transition (EMT) by suppressing the PSAT1-dependent GSK3β/Snail signaling pathway in esophageal squamous cell carcinoma (ESCC)." (PMID 37147729, 2023). "Additionally, in a mouse model of esophageal squamous cell carcinoma xenograft, phosphoserine aminotransferase (PSAT1) was found to be directly regulated by miR-340." (PMID 36013278, 2022). "PSAT1 expression is elevated in colon cancer, esophageal squamous cell carcinoma (ESCC) and NSCLC, and has been shown to enhance tumor growth, metastasis, and chemoresistance." (PMID 32824193, 2020). "Overexpression of LncRNA maternally expressed gene 3 (MEG3) could downregulate PSAT1 and suppress the activation of GSK-3β/Snail signaling pathway in esophageal squamous cell carcinoma (ESCC)." (PMID 37127605, 2023). "Consistently, in esophageal squamous cell carcinoma (ESCC) tissues, expression of PSAT1 is increased compared to adjacent non-cancer tissues and is significantly associated with disease stage." (PMID 35011702, 2022).